OAS1 (2'-5'-oligoadenylate synthetase 1)
Diseases named in the same sentence as OAS1 in open-access papers (continued):
Sharing a sentence is not in itself a finding about the gene and the disease.
infection (continued). "As key ISGs, OAS1, OAS2, and OAS3 are evolutionarily conserved and are associated with the early inflammatory response during infection." (PMID 34490145, 2021). "Second, it is worth investigating the allelic differential expression of OAS1 in the rs7967461 heterozygote-derived cells after infection with SARS-CoV-2." (PMID 35003084, 2021). "(E) CVB3 titers (percent titer normalized to EV) 48 hr post CVB3 infection (MOI=0.001) in OAS1 KO 293 T cells transfected with a control EV, p42, or p46." (PMID 34342578, 2021). "To investigate the role of the CaaX motif to the antiviral activity of OAS1, we expressed p42, p46, p42CTIL, or p46ATIL in OAS1 KO 293 T cells followed by infection with EMCV." (PMID 34342578, 2021). "(H) Quantification of EMCV 5′UTR by RT-qPCR from OAS1 KO 293 T cells transfected as in (G) at 24 hr post EMCV infection (MOI=0.001)." (PMID 34342578, 2021). "OAS1, OAS2, OAS3, and OASL expression levels are also directly linked to mycobacterial pathogenicity during the early post-infection period, as they can restrict MTB intracellular replication in macrophages by regulating cytokine secretion." (PMID 34490145, 2021). "We transfected plasmids encoding p42, p46, or an empty vector control in OAS1 KO 293 T cells and infected with EMCV at a multiplicity of infection (MOI) of 0.001 at 24 hr post-transfection." (PMID 34342578, 2021). "(C) Viral titers at 24 hr post EMCV infection (MOI=0.001) taken from OAS1 KO 293 T cells transfected with a control EV, p42, p46, or their corresponding catalytic mutants." (PMID 34342578, 2021). "(C) Viral titers at 24 hr post-infection with EMCV (MOI=0.001) in OAS1 KO 293 T cells transfected with a control EV, p42, and p46." (PMID 34342578, 2021). "The majority of the genes in this cluster were related to the immune response to infection including OAS-1/3, IFI44L, HLA-A and HLA-DRB-1/4." (PMID 34593881, 2021). "We determined the localization of p42 and p46 during EMCV infection by infecting OAS1 KO Huh7 cells expressing p42 or p46 with EMCV and then stained for OAS1 and dsRNA, followed by cLSM." (PMID 34342578, 2021). "(E) Viral titers quantified at 24 hr post-infection with EMCV at an MOI of 0.001 in OAS1 KO 293 T cells transfected with control EV, p42, p46, p42CTIL, or p46ATIL." (PMID 34342578, 2021). "(E) Quantification of EMCV 5′UTR in OAS1 KO 293T transfected as in (A) for 24 hr followed by EMCV infection for 24 hr (MOI=0.001)." (PMID 34342578, 2021). "(B) Quantification of EMCV 5′UTR by RT-qPCR at 24 hr post-infection with EMCV (MOI=0.001) in OAS1 KO 293 T cells transfected with a control EV, p42, and p46." (PMID 34342578, 2021). "Subsequently, the mRNA levels of RIG-1, PKR, and Mx1 gene began to increase at 12 h post-infection, whereas the expression of OAS1 continued to significantly decline (P < 0.01)." (PMID 32133381, 2020). "The expression of RIG-1, PKR, OAS1, Mx1, and Mx2 were significantly and positively correlated to each other during the entire infection (P < 0.01)." (PMID 32133381, 2020). "These genes’ expressions were decreased on day 33; however, compared with mock infection, IFNα, Rig-I, OAS-1, IRF7, MxA, and IL6 were also expressed at a statistically significant higher level." (PMID 32121148, 2020). "Real-time quantitative polymerase chain reaction was used to detect differences in the expression of the RIG-1, PKR, OAS1, Mx1, and Mx2 genes at various time points post-infection." (PMID 32133381, 2020). "While OAS1 was up-regulated with similar kinetics to the Asian lineage strains, the magnitude was also notably higher during MR-1947 infection." (PMID 28152048, 2017). "We found OAS1 transcripts were up-regulated at 24hpi by both PR-2015 and P6-1966, although to higher levels during P6-1966 infection." (PMID 28152048, 2017). "We found that cells from people with the Neandertal-like haplotype express lower levels of OAS3 upon infection, as well as distinct isoforms of OAS1 and OAS2." (PMID 27899133, 2016).
infection (continued). "Taken together, our results have identified that a possible factor leading to higher human virulence of WNVNY99 is likely to be decreased viral RNA replication and lower induction of IFNβ, OAS1 and MxA early in MoDCs infection." (PMID 25884341, 2015). "DENV-2 infection significantly increases OAS1 mRNA but at earlier times, peaking at 6 h post-infection." (PMID 26411318, 2015). "In conclusion, infection of the flaviviruses WNV, Dengue virus and HCV seem to be inhibited by expression of the p46 OAS1 protein derived from the presence of the G allele of the rs10774671 SNP in the OAS1 gene." (PMID 25205466, 2014). "Functional assays of the OAS1 promoter by transient transfection should be conducted in equine cell lines derived from tissues involved in the early development of post-infection WNV disease, but such cell lines are currently unavailable." (PMID 20479874, 2010). "Total OAS1 SNP rs10774671-specific mRNA modestly increased in a time-dependent manner after infection." (PMID 19247438, 2009). "Similar OAS1 relocalization occurs upon infection by SARS-CoV-2." (PMID 41729072, 2026). "Moreover, infection with the M448R-deficient ASFV mutant leads to increased IRF1 protein stability and elevated expression of IRF1 target genes, including OAS1, OAS2, and ZBP1." (PMID 42262133, 2026). "However, as the infection resolved, OAS1 was downregulated in patients with mild and moderate disease." (PMID 41445728, 2025). "Notably, the interferon-induced gene OAS1, upregulated in both development and infection, resulting in the activation of its nearby ERVs." (PMID 40176799, 2025). "Furthermore, we found an effective induction of IFN type I and III production and the effector antiviral molecule OAS-1, when the cells are pretreated with poly I:C 12 h before the infection." (PMID 38140569, 2023). "Finally, we discovered that infection by certain pathogens significantly increases OAS1 expression, especially mycobacterium tuberculosis (log FC = 2.6, p = 0.01) and Zika virus (log FC = 5.8, p < 0.001), which were prone to immune escape." (PMID 37928544, 2023). "In light of this, we tested whether cytosolic sensors Oas1-3 and Mx1 would be upregulated in response to infection." (PMID 36678402, 2022). "To explore whether interferon treatment could prevent or reduce infection in vitro, we treated infection-permissive intestinal cells Caco224,25 (heterozygous for OAS1 rs10774671 and rs1131454) with IFN-β or IFN-λ 4 h before or after SARS-CoV-2 infection." (PMID 35835913, 2022). "The p42 isoform of OAS1 exhibited similar restriction of infection." (PMID 35421191, 2022). "The role of other cytosolic sensors of infection, including Oas1-3, remain poorly understood." (PMID 36678402, 2022). "Finally, we demonstrated that infection induces transcription of cytosolic innate immune sensors Mx1, Oas1, and Oas3 in vivo and in vitro." (PMID 36678402, 2022). "Also, the expression levels of SOCS-1, PKR, and OAS1 mRNA were higher in D3-MDMs than in MDMs when matching infection rate conditions were done (e.g., MDMs MOI 3 vs. D3-MDMs MOI), suggesting a direct effect of VitD3 on the regulation of these genes in D3-MDMs." (PMID 34634046, 2021). "In addition, Calu-3 cells increased their expression of Mx1 and OAS1 at hours 48 and 72 post-infection." (PMID 34578229, 2021). "We therefore hypothesized OAS1 p46, through its CaaX motif, is targeted to the endomembrane system and this targeting gives it enhanced access to vRNA during infection." (PMID 34342578, 2021). "It is noteworthy that the expression of PKR and OAS-1 in the case of IVA infection was suppressed." (PMID 34452467, 2021). "Next, we measured the expression of OAS1 and MxA following OAdmCherry infection." (PMID 31100952, 2019). "EHDV-TAU infection of untreated LNCaP-JAK1 cells induced only two ISGs (OAS1 and HLA-A)." (PMID 29441069, 2018).
infection (continued). "Various repressors of apoptosis such as Ilf3, Zmym2, Satb1, Ccl21 and Scd were downregulated and expression levels of inducers of apoptosis such as Daxx, Oas1, Lcn2 and Gng2 were upregulated with V3000 infection at 24 h pi resulting in an overall activation of the apoptotic pathway." (PMID 28446152, 2017). "We finally tested whether prior exposure to sterile P. aeruginosa filtrates would affect expression of OAS1 during HRV16 infection." (PMID 26599098, 2015). "However, mammalian influenza viruses strongly up-regulated the expression of Mx1 and OAS1 which was likely to be a reflection of the presence of viable but infected cells at 6 h of infection." (PMID 26642934, 2015). "LV-shDUSP1 infection enhanced mRNA expression of myxovirus resistance protein A (MxA), 2'-5'-oligoadenylate synthetase 1 (OAS1), ISG15 ubiquitin-like modifier (ISG15), chemokine C-X-C motif ligand 10 (CXCL10), and USP18 relative to those in LV-cont-infected cells (P < 0.05)." (PMID 25798824, 2015). "Furthermore, our IFN-β and OAS-1 quantification was done after 24 hours of infection, whereas–given our present findings–it is interesting to assess the expression of interferon-responsive genes in the time frame of 0–10 hours post-inoculation with the virus." (PMID 26599098, 2015). "In this regard, we found that interferon-inducible antiviral proteins, RSAD2, OAS1, were also upregulated in the period of late infection, suggesting that many of the proteins identified in this study are associated with inflammation, IFN activation, and the innate immune response." (PMID 25333634, 2014). "The mRNA expression of OAS1 was significantly increased (P < 0.05) after only 8 h of infection." (PMID 24712747, 2014). "Interestingly, 2′-5′OAS1 expression, which is required for RNase L activation, was similarly increased after infection with both rTGEV-wt and rTGEV-Δ7 viruses." (PMID 21695242, 2011). "Therefore, 2′-5′OAS1 expression during infection by rTGEV-wt and rTGEV-Δ7 was evaluated by quantitative RT-PCR (RT-qPCR)." (PMID 21695242, 2011). "TGEV-wt infection induced the expression of the 2′-5′OAS1, as expected." (PMID 21695242, 2011). "The increased sensitivity of such approaches make them more capable of measuring subtle differences in OAS1 promoter activity that may be important for inhibiting viral replication during the initial stage of infection." (PMID 20479874, 2010). "Till now, many researchers had reported that susceptibilities to infection SARS-CoV may associated with HLA, MXA, OAS-1 and CLEC4M gene polymorphisms, yet these results were variable in different populations." (PMID 18312678, 2008). "Till now, many researchers have reported that susceptibility to infection SARS-CoV may associate with HLA, MXA, OAS-1 and CLEC4M gene polymorphisms, yet the results are variable in different populations." (PMID 18312678, 2008). "Furthermore, SARS-CoV-2 D614G[Omicron spike] infection resulted in a significantly increased expression of ISGs Mx1, Oas1, and Viperin as well as Cxcl10, while pro-inflammatory mediators Cxcl1, Ccl2, and Il6 were not significantly altered in any group compared to the uninfected mice." (PMID 38742107, 2024). "Since Mx1, Oas1, and Oas2 were upregulated in cells that O. tsutsugamushi preferentially targets for replication (endothelial cells and MΦ), future studies utilizing knockdown or genetic deletions of these molecules are needed to delineate their role during infection." (PMID 36678402, 2022). "Indeed we observe the steady up-regulation of OAS1 during acute-infection." (PMID 26801061, 2016). "However, the most striking effect was present with IFN-λ1 pre-treatment followed by DENV-2 infection, that showed a pronounced increase in OAS1 expression from 6 to 18 h post-infection, at which time it peaked and then underwent a slow steady decrease, remaining high at 24 and 48 h." (PMID 26411318, 2015).
infection (continued). "While the multiple SNP associations of the OAS1 promoter with WNV susceptibility are likely due to linkage disequilibrium, our association data also suggest a potential functional mechanism by which OAS1 expression in response to infection might, in part, confer resistance to WNV." (PMID 20479874, 2010). "In contrast, untreated infection networks were dominated by inflammatory mediators (IL6, CXCL10, CCL2, VCAM1, SELE) and antiviral sensors (DDX58, OAS1, IFI44, IFI6), which reflect strong cytokine and interferon-driven immunity." (PMID 41480150, 2025). "The induction levels of antiviral genes—including DDX58, OAS1, OAS2, ISG15, MX2, IFI44L, RTP4, and IFNB1—were markedly reduced in KO cells compared to WT cells post-infection." (PMID 40872812, 2025). "In this study, OAS1 transcription was up-regulated at 6 and 16 hpi during ASFV infection compared to mock infection, indicating multifaceted host antiviral responses." (PMID 41153955, 2025). "Infection with WR-ΔE3 increased the mRNA levels of IFNα, IFNβ, and the ISGs OAS1, PKR, and IFIT3 as the infection duration increased." (PMID 40833106, 2025). "We found that interferon-stimulated genes, crucial for restricting respiratory virus replication early after infection, such as CXCL10, CXCL9, CXCL11, OAS1, OASL, and ISG15, were significantly upregulated in PCLS 72 h post-infection." (PMID 41239423, 2025). "For this purpose, PBE cells were challenged with SIV H1N1 or H3N2 and the expression of IFN-β and the antiviral factors Mx1, Mx2, IFITM1, OAS1, OAS2, and OASL were evaluated at different hours post-infection." (PMID 40565228, 2025). "RT-qPCR analysis of RNA isolated from hGBOs at 48 h post-infection revealed a robust upregulation of IFNB1 and IFNB1-stimulated IFIT1, MX1, CXCL10, and OAS1." (PMID 41255708, 2025). "Membrane‐bound OAS1 is more efficient in recognizing SARS‐CoV‐2 RNA than cytosolic OAS1 and thus plays a role in activating RNase L during infection by this virus." (PMID 39727035, 2024). "While the number of significantly upregulated genes decreases to 37, these genes (e.g., ISG15, IFI6, IFI44L, HP, OAS1, IFI44, OASL, and IFI27) likely play a crucial role in the response to the progressing infection." (PMID 39282474, 2024). "The significant involvement of Interferon-Stimulated Genes (ISGs) like ISG15, OAS1, and MX1 throughout the infection period underscores the critical role of interferon responses." (PMID 38957806, 2024). "Primary human Sertoli cells infected with either 5 or 10 MOI of the Zika virus showed a prominent, dose dependant, increase in the expression of ISGs including ISG15, OAS1, IRF1, and IFI6 48 hours post-infection, compared to uninfected controls at 8 hours." (PMID 39621805, 2024). "We found that the type I interferon (IFN-I)-related genes, DDX60, IFI16, IRF7, ISG15, OAS1, and STAT1, were more highly expressed after Omicron breakthrough infection." (PMID 39835127, 2024). "The 17 DEGs upregulated after infection with huH1N1 were shared with the swH1N1 infection (DDX58 (RIG-I), RSAD2 (Viperin), MX2, MX1, OAS1, ANGPTL4, IRF7, ISG15, IFIT1, ISG12(A), DDX60, BST2, IFI44, XAF1, LGALS3BP, RTP4, and IFI6)." (PMID 39247193, 2024). "Two common antiviral genes, OAS1 and MX1, showed increased mRNA levels during the course of infection." (PMID 37724882, 2023). "In the present study, it was found that OAS1 and IFI6 were overexpressed in individuals with a high viral load of infection." (PMID 37389217, 2023). "In line with previous reports suggesting mild interferon responses to SARS-CoV-2 infections, OAS1 and IRF7 were only slightly elevated in THP-1 cells after infection with SARS-CoV-2 under normoxia and hypoxia." (PMID 37377965, 2023). "At the same time, after the knockdown of the expression of batMDA5, infection with VSV-GFP significantly inhibits the expression of batIFNβ and interferon-stimulated related genes batMX1 and OAS1." (PMID 35677039, 2022).
infection (continued). "Further, SARS-CoV-2 infection significantly induced these ISGs in ferret tracheal biopsy samples collected on day 3 after infection compared with mock-treated animals (p < 0.01 for MX1; and p < 0.05 for MX2, ISG15, and OAS1)." (PMID 36298734, 2022). "In NHBE cells, only MX1, MX2, and OAS1 were significantly over-expressed in SARS-CoV-2-infected cells compared with mock infection (p < 0.05 for MX1 and OAS1; and p < 0.01 for MX2)." (PMID 36298734, 2022). "Most of the well-studied ISGs—such as Protein Kinase R (PKR), 2’-5’-Oligoadenylate Synthetase 1 (OAS1), IRF7, and RNAseL—require activation by infection-dependent signals, whereas select other ISGs—such as IRF1—are synthesized in a constitutively active form." (PMID 33808506, 2021). "(E) Quantification of EMCV 5 ́UTR by RT-qPCR from OAS1 KO 293 T cells expressing a control EV, p42, p42 CFK mutant, p46, and p46 CFK mutant at 24 hr post EMCV infection (MOI=0.001)." (PMID 34342578, 2021). "Some interferon stimulated genes such as OAS1, OAS3, MX1, and RSAD2 that were strongly induced by rDEN2Δ30 infection are also known to be regulated in natural infection." (PMID 34031380, 2021). "(C) Quantification of EMCV 5 ́UTR by RT-qPCR from OAS1 KO 293 T cells expressing a control EV, p46, p46ATIL, and p46 alanine substitution mutants 1–9 at 24 hr post EMCV infection (MOI=0.001)." (PMID 34342578, 2021). "The principal effect of YTHDF3 depletion on the innate host response to PVSRIPO infection was dampened induction of ISGs (STAT1, MDA5, IFIT1, ISG15, OAS1)." (PMID 33849973, 2021). "(D) Quantification of EMCV 5′UTR by RT-qPCR from OAS1 KO 293T expressing a control EV, p42, p46, p42CTIL, or p46ATIL at 24 hr post EMCV infection (MOI=0.001)." (PMID 34342578, 2021). "(H) Quantification of EMCV 5 ́UTR by RT-qPCR from OAS1 KO 293 T cells expressing EV, p46, p46 truncation mutants Δ12aa, Δ22aa, and Δ32aa, and p42CTIL at 24 hr post EMCV infection (MOI=0.001)." (PMID 34342578, 2021). "(B) Quantification of EMCV 5′UTR by RT-qPCR in OAS1 KO 293 T cells expressing a control EV, p42, p46, or their corresponding catalytic mutants (250 ng) at 24 hr post EMCV infection (MOI=0.001)." (PMID 34342578, 2021). "The 2′-5′-oligoadenylate synthases (OAS1-3, OASL) were 1.6–7-fold induced upon infection to produce 2′-5′-adenylic acid as second messenger and activator of RNaseL for viral RNA degradation." (PMID 34777295, 2021). "The expression of some ISGs like OAS1/2/3 and the upstream regulator of the IFNs pathway IRF6, were unresponsive in patients with severe infection." (PMID 33679778, 2021). "IFNα, IFNβ, IFNλ1, Rig-I, IRF3, IRF7, OAS-1, MxA, IL6, IL8, and TNFα expressions were increased at either day 1 or day 2 in HFDPCs post-infection or on both days." (PMID 32121148, 2020). "Taken together, it was indicated that β-catenin inhibited BPIV3 infection via activation of the innate immune signaling pathway encompassing IFN-β and OAS1." (PMID 32127006, 2020). "In the present study, we found that the expression of antiviral genes (e.g., PKR, OAS1, and Mx2) and inflammatory cytokines (e.g., IFN-α and TNF-α) were significantly reduced within 0–4 h post-infection." (PMID 32133381, 2020). "The expressions of IFNα, IFNβ, IFNλ1, Rig-I, OAS-1, MxA, IL6, IL8, and TNFα were increased at either day 1 or day 2 in WS1 post-infection or on both days." (PMID 32121148, 2020). "Innate antiviral defense genes, namely ISGs (e.g., MX1, OAS1, STAT1, STAT2, ISG15), are upregulated early in fatal infection and their expression increases dramatically throughout infection indicative of dysregulated innate immune response." (PMID 32992829, 2020). "Interestingly, MDA-5 (for melanoma differentiation-associated gene 5), MX1 (for myxovirus resistance 1), OAS1 (for oligoadenylate synthetase 1), ISG20 (for Interferon Stimulated Exonuclease Gene 20) and RIG-1 (for reticnoic acide-inducible gene 1) were up-regulated at day 5 after infection." (PMID 33490061, 2020).